MSANTD3-TMEFF1 (MSANTD3-TMEFF1 readthrough)
Synonyms: formerly C9orf30-TMEFF1
Gene: Protein-coding gene on chromosome 9 (100,442,271 to 100,577,636, forward strand). Ensembl gene ENSG00000251349.
Genetic constraint (gnomAD): Loss-of-function variants: 18 observed, 46.35 expected, observed/expected ratio (o/e) 0.39, 90% interval 0.27 to 0.58. The upper end of that interval is the gene's LOEUF score, 0.58, which puts it in group 2 of 6, group 1 being the genes least tolerant of losing a copy. Missense variants: 352 observed, 422.64 expected, observed/expected ratio (o/e) 0.83, 90% interval 0.76 to 0.91. Synonymous variants: 138 observed, 138.89 expected, observed/expected ratio (o/e) 0.99, 90% interval 0.86 to 1.14.